GRHL2 (grainyhead like transcription factor 2)
Diseases named in the same sentence as GRHL2 in open-access papers (continued):
Sharing a sentence is not in itself a finding about the gene and the disease.
gastric cancer (13 papers, 2012 to 2023). A primary or metastatic malignant neoplasm involving the stomach. "Here we aim to explore the effects of Grhl2 on invasion and migration of gastric cancer and further clarify its possible underlying mechanisms." (PMID 28067907, 2017). "Thus, we concluded that downregulation of Grhl2 in gastric cancer may, at least in part, be caused by TGFβ signaling pathways." (PMID 28067907, 2017). "GRHL2 represses mesenchymal factors in a variety of cancers, including breast, ovarian colorectal, and gastric cancers." (PMID 37761927, 2023). "Mir-1290 in gastric cancer-derived exosomes can inhibit T cell proliferation through the grainyhead-like 2 (Grhl2)/zinc finger E-box binding homeobox 1 (ZEB1)/PD-L1 axis and participate in immune tolerance." (PMID 36341377, 2022). "Ectopic expression of GRHL2 in a gastric cancer cell lines inhibited proliferation, invasion and migration, and promoted apoptosis." (PMID 35269877, 2022). "Gastric cancer (GC) cell-derived exosomes contain miR-1290, which suppresses T cell activation by targeting the grainyhead-like 2 (GRHL2)/zinc finger E-box binding homeobox 1 (ZEB1) pathway, thereby provoking immune escape." (PMID 35562884, 2022). "In the previous study, we have reported that Grhl2 functioned as a tumor suppressor in proliferation and apoptosis of gastric cancer." (PMID 28067907, 2017). "In this study, our results demonstrated that TGFβ-induced EMT can be abrogated by overexpression of Grhl2 in gastric cancer." (PMID 28067907, 2017). "Meanwhile, the metastatic tumor model further confirmed the inhibition of Grhl2 on metastasis of gastric cancer." (PMID 28067907, 2017). "On the other hand, we constructed an in vivo metastatic model to study the effect of Grhl2 on the metastatic potential of gastric cancer cells." (PMID 28067907, 2017). "Thereby, to a certain extent, clarifying that a systematic mechanism of Grhl2 suppresses the progression of gastric cancer." (PMID 28067907, 2017). "In conclusion, our study identified Grhl2 as a tumor suppressor, through regulation of TGFβ signaling pathways, involved in the occurrence and development of gastric cancer." (PMID 28067907, 2017). "This contradicts the findings in gastric cancer that GRHL2 suppresses tumour growth by inducing apoptosis and inhibiting cell proliferation." (PMID 26887977, 2016). "Consistently, GRHL2 was shown to inhibit EMT in gastric cancer, oral cancer and pancreatic cancer." (PMID 32676163, 2020). "Here we further investigate the effects of Grhl2 on invasion and migration of gastric cancer." (PMID 28067907, 2017). "Which one is the first step in gastric cancer progression (Grhl2 downregulation or EMT process)?" (PMID 28067907, 2017). "Finally, subcutaneous xenograft model further validated the growth inhibition and EMT reversal of Grhl2 on gastric cancer in vivo." (PMID 28067907, 2017). "Finally, the results of subcutaneous xenograft model indicated that Grhl2 suppresses the growth of gastric cancer and reverses EMT process in vivo." (PMID 28067907, 2017). "This is an intriguing question and relates to whether Grhl2 could be seen as a predictor in early gastric cancer." (PMID 28067907, 2017). "Moreover, metastatic model indicated that Grhl2 significantly inhibits the metastatic potential of gastric cancer." (PMID 28067907, 2017). "Meanwhile, we reveal the relationship between Grhl2 and TGFβ signaling pathways in gastric cancer." (PMID 28067907, 2017). "Grhl2 reduces the expression of MMP-2, MMP-7 and MMP-9, which may partly explain the inhibitory effect of Grhl2 on invasion and migration of gastric cancer." (PMID 28067907, 2017). "Thus, our results demonstrated that Grhl2 suppresses the metastasis of gastric cancer in vivo." (PMID 28067907, 2017). "Moreover, inhibition of TGFβ signaling pathway can restore Grhl2 expression in gastric cancer." (PMID 28067907, 2017).
gastric cancer (continued). "In addition, it was the first time for this findings that expression of MCM4PRKDC, and UBE2V2 at 8q11.21, or YWHAZANKRD46ZNF706, and GRHL2 at 8q22.3 was co-regulation and was concordantly up-regulated in the samples of gastric cancer with amplification at 8q11.21 or 8q22.3." (PMID 22559327, 2012). "The results showed that EMT‐promoting factors SNAI1 and SNAI2 were significantly downregulated, while EMT repressors GRHL2 and OVOL1 were significantly upregulated, suggesting that zyxin negatively regulates EMT in gastric cancer cells." (PMID 37667739, 2023). "Human gastric cancer cell lines SGC7901 and MKN45 were used in this study, and both the cell lines were infected with Grhl2 expression vector." (PMID 28067907, 2017). "Taken together, our findings proved that Grhl2, functioned as a tumor suppressor, reduces the invasion and migration through inhibition of TGFβ-induced EMT in gastric cancer." (PMID 28067907, 2017). "Therefore, we tested the changes of MMP-2, MMP-7 and MMP-9 after Grhl2 overexpression in both SGC7901 and MKN45, so as to preliminarily clear the possible mechanisms by which Grhl2 inhibits invasion and migration of gastric cancer." (PMID 28067907, 2017). "However, the deep mechanisms by which Grhl2 inhibits the progression of gastric cancer were not clearly described." (PMID 28067907, 2017). "Another example is macrophage-derived EVs in gastric cancer (GC), which contain high levels of miR-130b-3p and promote survival, migration, invasion and angiogenesis in GC cells through the modulation of MLL3 (mixed-lineage leukemia protein 3) and GRHL2 (grainyhead-like protein 2 homolog)." (PMID 34064331, 2021). "In the present study, Grhl2 reduces MMP-2, MMP-7 and MMP-9 expression, which is partly explained by the mechanism by which Grhl2 inhibits gastric cancer cell invasion and migration, but this is obviously not enough." (PMID 28067907, 2017). "Furthermore, in our preliminary experiments, high expression of Grhl2 was also seen in NCI-N87 gastric cancer cells, which represent a kind of high differentiation of gastric cancer cell line (data not show)." (PMID 28067907, 2017).
hearing loss (12 papers, 2013 to 2025). "Grhl2 loss of function has been found to cause micrognathia and kidney abnormalities in mice and is associated with hearing loss in humans." (PMID 37364051, 2023). "The majority of hearing-loss-related variants are truncating variants, while missense and deep intronic variants seem to be more likely to be associated with other GRHL2-related pathologies." (PMID 33810548, 2021). "We aimed to evaluate the genetic etiology of hearing loss in a family with moderate late-onset hearing loss using next-generation sequencing and to conduct a review of reported variants in the GRHL2 gene." (PMID 33810548, 2021). "Reviewing the known GRHL2 variants associated with hearing loss, it can be concluded that they are more likely to be truncating variants, while the associated onset of hearing loss is variable." (PMID 33810548, 2021). "The clinical presentation of GRHL2-related hearing loss is reported to be moderate, progressive, bilateral, and late-onset." (PMID 33810548, 2021). "Reviewing known GRHL2 variants associated with hearing loss, we can conclude that they are more likely to be truncating variants, while the associated onset of hearing loss is variable." (PMID 33810548, 2021). "Both patients reported here with the novel truncating variant had had their hearing loss diagnosed in their early adulthood, the daughter when she was 28 and the mother when she was 39, which is consistent with the reported onset in GRHL2." (PMID 33810548, 2021). "This study aimed to evaluate the genetic etiology of hearing loss in two members of a family with moderate late-onset hearing loss and to conduct a review of the known GRHL2 variants associated with hearing loss." (PMID 33810548, 2021). "The purpose of this study was to identify a precise estimation of the association between rs3735715 polymorphism in GRHL2 gene and susceptibility of noise-induced hearing loss." (PMID 30853467, 2020). "In this regard, many studies have evaluated the association between GRHL2 and noise-induced hearing loss, although the results are ambiguous and conflicting." (PMID 30853467, 2020). "Hearing impairment is another pathologic condition linked to GRHL2 mutation, where sequencing of the gene loci DFNA28 on chromosome 8q22 in a large American family is associated with progressive autosomal dominant hearing loss." (PMID 32974388, 2020). "The progressive hearing loss of DFNA28 and age-related hearing loss suggest that GRHL2 is essential for maintaining epithelial cells." (PMID 26915689, 2016). "We report on a second DFNA28-causing mutation and the first splice site mutation in GRHL2 in a family affected with non-syndromic hearing loss." (PMID 23813623, 2013). "Mutations in GRHL2 have been identified to cause DFNA28 progressive hearing loss in humans." (PMID 41255877, 2025). "Variants in the GRHL2 gene are an extremely rare cause of dominantly inherited hearing loss." (PMID 33810548, 2021). "Rs3735715 polymorphism in GRHL2 gene may influence the susceptibility of noise-induced hearing loss." (PMID 30853467, 2020). "Besides, other polymorphic sequence variants in GRHL2 have also been implicated in age-related hearing impairment and noise-induced hearing loss." (PMID 29110737, 2017). "Nevertheless, the severity of her hearing loss might be due to the combined genetic GRHL2 defect and an environmental cause, since she was exposed to occupational noise and some GRHL2 variants have previously been associated with noise-induced hearing loss in a Chinese population." (PMID 33810548, 2021). "The purpose of this study was to examine the associations between genetic variations in the EYA4, GRHL2 and DFNA5 genes and the risk to noise-induced hearing loss (NIHL) in a Chinese population." (PMID 26400775, 2015).
hearing loss (continued). "Other than hearing loss, the patients reported here had no additional clinical characteristics reported to be associated with the GRHL2 genetic defect, such as diffuse capillary malformations and undergrowth, ectodermal dysplasia, or eye abnormalities." (PMID 33810548, 2021). "In GRHL2, a total of 4 genetic variants were identified, but none were associated with hearing loss in Korean patients." (PMID 25781927, 2015). "In this study, we analyzed six proteins causing progressive hereditary hearing loss, five of which (CX31, CRYM, GRHL2, DFNA5, and ATP6B1) do not recapitulate human symptoms in the mouse model." (PMID 26915689, 2016).
lung carcinoma (12 papers, 2016 to 2025). "Among them, GRHL2 was reported to be associated with EMT status in lung cancer, and FBLN1 was once reported as novel diagnostic biomarkers in both tissue and serum of lung cancer patients." (PMID 41214581, 2025). "Different from E2F3 and TFAP2C, GRHL2 can suppress tumor metastasis by regulating of transcriptional activity of RhoG in lung cancer." (PMID 30967126, 2019). "Grhl2 is a key regulator of the E/M hybrid state of lung cancer cells, and Hnf4a is the master effector of mesenchymal-epithelial transition (MET) and is able to maintain hepatocyte identity." (PMID 29540203, 2018). "Further, we show that H1975 lung cancer cells can display a stable hybrid E/M phenotype and migrate collectively, a behavior that is impaired by knockdown of GRHL2 and another previously identified PSF - OVOL." (PMID 27008704, 2016). "Further, we show experimentally that partial EMT phenotype can be observed stably at a single-cell level in H1975 lung cancer cells in vitro, and knockdown of OVOL and GRHL2 can impair collective cell migration - a hallmark of the hybrid E/M phenotype - and drive a complete EMT." (PMID 27008704, 2016). "In the lung carcinoma cell line (E114), DeepHistone recovered E2F3, TFAP2C and GRHL2." (PMID 30967126, 2019).
prostate carcinoma (12 papers, 2016 to 2024). A carcinoma that arises from epithelial cells of the prostate gland. "EHF has been previously implicated in ovarian, gastric and prostate cancer but our findings point to cooperative roles of GRHL2 target genes including EHF and E2Fs in sustaining proliferation." (PMID 36691073, 2023). "The ability to suppress EMT has also been noted in prostate cancer, another cancer driven by a steroid hormone receptor (AR), and the genes regulated by GRHL2 are linked to disease progression." (PMID 31084623, 2019). "Meanwhile, DNMT3A has been highlighted as a key repressor of epithelial genes, including CDH1 and GRHL2, in a prostate cancer-associated fibroblast-induced EMT model." (PMID 31372511, 2019). "In promoting proliferation in ART, CREB5 exhibited a strong degree of interaction with known AR transcription machinery, including FOXA1, HOXB13, and GRHL2, as well as novel prostate cancer regulators TBX3 and NFIC." (PMID 35550030, 2022). "The role of GRHL2 in prostate cancer seems to be mainly oncogenic, as its expression is higher in prostate cancer tissue samples." (PMID 32974388, 2020). "In addition to driving AR expression, GRHL2 also acts as an AR transcriptional co-activator that enhances the oncogenic AR signaling pathway in prostate cancer progression." (PMID 32974388, 2020). "5hmC-sequencing in cfDNA identified a subgroup of prostate cancer patients with preexisting activation (5hmC hypermethylation) of gene sets involving AR, FOXA1 and GRHL2 before initiating ADT." (PMID 37904926, 2024). "Topics enriched in Samples 4 and 16 include genes such as AR, GRHL2, FOXA1, SLC43A1, WNT7B, which are known downstream players active in prostate cancers with ERG expression." (PMID 34911933, 2021). "On the contrary, NDRs in prostate cancer-specific enhancers involved in enhancer–promoter loops are enriched for motifs for TFs such as FOXA1, GRHL2, ETS, and AR." (PMID 31515496, 2019). "For example, HOXC6 and DLX1 genes, which are biomarkers and key players of prostate cancer development as well as genes involved cell cycle (CDK4, CDC23, MYC) and androgen signaling (AR, GRHL2) are found." (PMID 31515496, 2019). "Second, miR-145 has been shown to induce a partial EMT in prostate cancer cells, and similar to OVOL and GRHL2, can drive MET when overexpressed." (PMID 27008704, 2016). "On the contrary, prostate-cancer-specific enhancers had motifs for FOXA1, GRHL2, AR, and ETS." (PMID 31515496, 2019). "Importantly for six of the eight candidates, (TRIB1, PCA3, GRHL2, ACTG2, GSN, and MXI1) we were able to confirm the differential expression of the genes that harbor these STRs using a large dataset of prostate cancers compared to adjacent non-malignant cells." (PMID 29203868, 2017).
colorectal cancer (8 papers, 2016 to 2023). A primary or metastatic malignant neoplasm that affects the colon or rectum. "In support of this, similar to our results in LN229 cells, GRHL2 was shown to accelerate cell-cycle progression of colorectal cancer cells, leading to an aberrant increase in cells in the S and G2/M phases." (PMID 37761927, 2023). "The GRHL2 mRNA level was significantly increased in colorectal cancer tumor samples compared with the matching normal colorectal samples." (PMID 34771571, 2021). "GRHL2 was also upregulated in colorectal cancer and in liver and lung metastatic samples compared with normal colon tissue, and GRHL2 was expressed in all CTC cell lines." (PMID 34771571, 2021). "Overall, GRHL2 was upregulated in colorectal cancer and in liver and lung metastatic samples compared with normal colon tissue, and GRHL2 was expressed in all CTC cell lines." (PMID 34771571, 2021). "Moreover, GRHL2 knockdown in colorectal cancer cells inhibits cell proliferation by targeting ZEB1." (PMID 32571262, 2020). "Cancer types in which the expression of both GRHL2 and S100A10 is simultaneously increased include hepatocellular carcinoma, non-small-cell lung cancer, colorectal cancer, and pancreatic ductal adenocarcinoma." (PMID 34356598, 2021). "Another known direct target of GRHL2 is RAB25, a tumor-suppressor gene in colorectal cancer." (PMID 34771571, 2021).
age-related hearing impairment (7 papers, 2013 to 2023). "In humans, mutations in GRHL2 have been implicated in autosomal dominant and age-related hearing loss and ectodermal dysplasia (with abnormal dentition)." (PMID 37364051, 2023). "Our detailed investigation into the expression patterns of GRHL2 will be useful for researching the disease mechanisms of DFNA28 and of age-related hearing loss, with our primate model offering more reliable information than rodents." (PMID 26915689, 2016). "Additionally, the homeostatic roles played by this family are often not apparent until later in life, as is the case with Grhl2 loss ultimately leading to age-related hearing impairment." (PMID 27756203, 2016).
autosomal dominant deafness (7 papers, 2013 to 2021). "In this study, we performed a genetic analysis of EYA4 and GRHL2 in 87 unrelated Korean patients with autosomal dominant non-syndromic hearing loss (NSHL)." (PMID 25781927, 2015). "In this study, 10 SNPs located in the POU4F3 and GRHL2 genes, which are regarded as the genes of autosomal dominant deafness, taking into account noise exposure, were analyzed in a Chinese sample set." (PMID 27271650, 2016). "Haploinsufficiency for GRHL2 has been implicated in autosomal-dominant deafness, but mutations have not yet been associated with any skin pathology." (PMID 25152456, 2014). "More than 10 years ago, a c.1609_1610insC mutation in the grainyhead-like 2 (GRHL2) gene was identified in a large family with nonsyndromic sensorineural hearing loss, so far presenting the only evidence for GRHL2 being an autosomal-dominant deafness gene (DFNA28)." (PMID 23813623, 2013).
sarcoma (7 papers, 2017 to 2023). A usually aggressive malignant neoplasm of the soft tissue or bone. "On the other hand, GRHL2 activates the expression of miR-200 family members through direct promoter binding in oral, ovarian cancers and sarcoma." (PMID 32974388, 2020). "The revised model was able to reproduce robustly the key features of experiments in sarcoma cells, such as the synergistic induction of E‐cadherin levels upon overexpression of both GRHL2 and miR‐200, and predicted how epigenetic regulation of GRHL2 can modulate MET." (PMID 28548388, 2017). "On one hand, GRHL2 directly suppresses the expression of the EMT inducer ZEB1 in breast, ovarian, bladder cancers, and sarcoma." (PMID 32974388, 2020). "Similarly, GRHL2 – a transcription factor that can inhibit EMT – can be methylated in sarcomas as compared to carcinoma, thus rewiring the circuit regulating EMT in sarcomas." (PMID 28548345, 2017). "For instance, overexpression of GRHL2 did not drive MET in the RD and 143B human sarcoma cell lines." (PMID 28548388, 2017).
bladder cancer (6 papers, 2022 to 2023). "Moreover, expression of GRHL2 is decreased in human bladder cancer samples, and downregulation of GRHL2 increases the proliferation rate of bladder cancer cells." (PMID 35269877, 2022). "This strategy identified a large module of Luminal TFs, including known Luminal-associated TFs (e.g., FOXA1/GATA3/PPARG), as well as TFs with yet unexplored roles in Luminal bladder cancer biology (e.g., HES1, FOXQ1, ZBTB7C, MECOM, GRHL2/3, and TBX3)." (PMID 36944729, 2023).